EGFR (epidermal growth factor receptor)
Diseases named in the same sentence as EGFR in open-access papers (continued):
Sharing a sentence is not in itself a finding about the gene and the disease.
tumor (continued). "ENO1 and RAC1 also showed high levels of expression in EGFR mutant LUADs aligning with previous studies demonstrating that ENO1 expression is greater in LUAD tumor samples relative to non-cancerous tissue, and the RAC1 splice variant RAC1B enhances LUAD tumor formation in vivo." (PMID 38260835, 2023). "Because of the higher avidity of the bivalent anti-EGFR TMs, they could direct the Nb-adCAR-T cells to tumor cells with low EGFR expression levels, while the monovalent TMs could only direct the Nb-adCAR-T cells to tumor cells with high EGFR expression levels." (PMID 36761751, 2023). "However, a pooled analysis of two trials evaluating the combined biomarkers of KRAS, NRAS, BRAF, and PIK3CA showed a significantly reduced benefit from anti-EGFR therapy in patients with any mutant tumor compared with patients with all wt tumors (interaction tests P < 0.05 for PFS, OS, and ORR)." (PMID 37974093, 2023). "Moreover, studies in vivo and in vitro have reported that EGFR overexpression was involved in corticotroph tumor formation, cell proliferation, Pomc expression, and ACTH secretion via mitogen-activated protein kinase (MAPK) activation, and these factors are inhibited by EGFR inhibitors." (PMID 36672445, 2023). "Tumour cells with activated EGFR could produce EVs disseminating EGFR itself or its ligands." (PMID 37296932, 2023). "This improvement may be attributed to the heightened radiosensitivity of EGFR-positive NSCLC cells and the ability of cranial RT to efficiently clear intracranial tumours while potentially facilitating better EGFR-TKI penetration through the blood–brain barrier." (PMID 38313214, 2023). "In addition, the effective blockade of angiogenesis signaling through the VEGF receptor and EGFR signaling pathways could have been useful in controlling the tumor growth." (PMID 37873790, 2023). "This heterogeneity in GBM may elucidate the lack of success observed in targeted treatments aimed specifically at tumor biomarkers, including drugs like cetuximab, gefitinib, erlotinib (targeting EGFR), bevacizumab (targeting VEGF), and cilengitide (targeting integrin)." (PMID 38002561, 2023). "Therefore, in the present study, we hypothesized that Curcumin might enhance the anti-tumor effects of Lenvatinib as a tyrosine kinase inhibitor and that the anti-EGFR potential of Curcumin could help overcome Lenvatinib resistance in HCC." (PMID 36831279, 2023). "Reduction of Ki-67 was reported in TNBC tumors treated with gefitinib and with an EGFR inhibitor in combination with fingolimod, as well as in human BC cell xenograft tumors treated with platycodin D, reinforcing our conclusions of significant decreases in tumor cells proliferation." (PMID 37568789, 2023). "However, activating the EGFR pathway in the tumor cells activated c-Src, which subsequently downregulated LAR, suggesting this process could be synergistic with DAPK inactivation in order to evade apoptotic cell death." (PMID 38136610, 2023). "The coexistence of EGFR mutations and ALK rearrangements in NSCLC remains a subject of debate, with theories suggesting that the two alterations may either exist in different cells within the same tumor or in the same cells." (PMID 36835536, 2023). "A more recent publication suggested that higher fluence rates may lead to increased EGFR activation, thereby contributing to a larger tumor burden compared to lower fluence rates, providing a possible partial explanation for the enhanced efficacy of lower fluence rates." (PMID 36839652, 2023). "We speculate that the low EGFR abundance after TKI treatment may indicate that more EGFR‐mutated tumor cells are removed, fewer tumor cells are resistant to immunotherapy, and residual tumor cells are more likely to respond to ICIs." (PMID 37723846, 2023).
tumor (continued). "Moreover, DNA methylation could be a novel tumor cellular state, which helps to accurately distinguish the tumor heterogeneity of EGFR-Tkis." (PMID 36778111, 2023). "In addition, the CHP score was found to be related to resistance against a variety of anti-tumor drugs, including anti-angiogenesis inhibitors and platinum genotoxins, while EGFR pathway inhibitors were found to possibly be sensitizers for high CHP score tumors." (PMID 36761982, 2023). "Importantly, based on our data for 7 Ba/Sq samples, we were able to identify higher enhancer activity associated with potential key genes in Basal tumour biology, including cell surface receptors (IL7R, OSMR, EGFR, MET) and transcriptional regulators (BNC2, HMGA2, KLF7, NR3C1)." (PMID 36944729, 2023). "However, EGFR gene mutations only exist in tumor tissues, particularly in NSCLC, and do not exist in healthy tissue cells." (PMID 37390230, 2023). "If both NTSR1 and EGFR are enriched in the tumor cells, SR48692 and osimertinib may be used." (PMID 37508387, 2023). "However, efficacy of EGFR antibodies seems to be restricted to patients whose primary tumour is located on the left site of the colon, whilst patients harbouring a tumour situated proximal from the left splenic flexure should rather receive bevacizumab in first line." (PMID 37466791, 2023). "Cetuximab, a monoclonal antibody against EGFR, blocks EGFR pathway signaling mainly by competitively suppressing the binding action of EGFR to related ligands, which can kill EGFR‐positive OS cells by enhancing the cytolytic function of NK cells and inhibit distant tumor invasion and angiogenesis." (PMID 37441462, 2023). "In addition, comparing with the initial tumor size, the size of the lesion may be much reduced due to the previous response of the first-line EGFR-TKI, which makes the tissue re-biopsy impossible." (PMID 36900237, 2023). "However, within this tumor subset, a subgroup of xenopatients and m‐colospheres displayed proliferative ability independent of EGFR (resistance to EGFR inhibition), associated with overexpression and actionability of insulin‐like growth factor 2 (IGF2)." (PMID 36862005, 2023). "In clinical trials, even tumors without EGFR mutation responded well to EGFR-TKIs, which strongly suggested not only the tumor cells themselves but also potentially tumor-specific immune responses might be the targets of EGFR-TKIs." (PMID 36949948, 2023). "In addition, Liu and colleagues established a method named PLA‐RPA‐TMA assay: two proximity ligation assay (PLA) probes recognize biomarkers such as LMP or EGFR protein on tumor‐derived EVs in NPC, and then generate the unique surrogate DNA signal for these biomarkers." (PMID 37306659, 2023). "Since the concordance level in KRAS mutational status between tumor tissue and ctDNA is high (∼92%), the detection of KRAS mutations in ctDNA has been proposed as a rapid and minimally-invasive alternative method to tissue biopsy for predicting the response to anti-EGFR treatment." (PMID 36831626, 2023). "Interestingly, β4 upregulation mediated epidermal growth factor receptor (EGFR) signalling, indicating that the β4 subunit may have a role to play in facilitating tumour migration." (PMID 37173998, 2023). "We reasoned that tumor microenvironment may play a role in development of resistance to EGFR-TKIs." (PMID 36817465, 2023). "The principal drug targets for existing drugs include insulin‐like growth factor (IGF)‐R, EGFR, PDGF/PDGFR, mTOR, VEGFR, and Aurora kinase pathways linked to cellular growth, immune checkpoint pathways linked to immunity, relay immune cell therapy, and tumor vaccines." (PMID 37441462, 2023). "Furthermore, EGFR knockdown reduced the resistance of TRPV1-transfected tumor cells to cisplatin." (PMID 37165076, 2023).
tumor (continued). "In addition, tumor xenograft research in a mouse model revealed that tumor-derived exosomes may be able to transfer EGFR to tumor blood vessels, which may then promote the tumors’ development and angiogenesis." (PMID 36834471, 2023). "The fact that a low EGFR expression tends to be associated to an immune “hot” environment suggests the possibility of a dual positive effect for EGFR inhibition in EGFR-activated HNSCCs, where tumor cell growth could be suppressed alongside an immune response enhancement." (PMID 37819239, 2023). "One patient with EGFR amplification experienced a persistent partial response to cetuximab in the third‐line setting, while another UrC patient with immunohistochemically proven EGFR overexpression experienced a transient 55% decrease in tumour size with gefitinib treatment." (PMID 36670542, 2023). "Additionally, EGFR-mutant NSCLCs were generally non-smokers with low PD-L1 expression and with a low tumor mutation burden." (PMID 38001917, 2023). "Targeting specific tumor characteristics such as proliferation (chemotherapy, radiotherapy, and EGFR inhibitors) and network integration (e.g., ion channel modulators) can eliminate specific tumor populations and may induce differentiation to improve GBM treatment efficiency." (PMID 37109434, 2023). "Indeed, changes in the EGFR endocytic and recycling pathways in tumor cells may derail the spatial distribution of the EGFR, leading to a persistent oncogenic signaling output." (PMID 37270563, 2023). "Therefore, the combination of targeting CD16a, EGFR and PD-L1 could provide significant clinical benefit also in view of the recently reported finding that tumor-specificity can be elevated by simultaneous targeting EGFR and PD-L1 by a bispecific antibody." (PMID 37081888, 2023). "The main driver mutations of primary tumours with LM were determined by NGS, including EGFR L858R (10, 35.7%), EGFR 19del (6, 21.4%), EGFR L858R + MET amplification (1, 3.6%), EGFR L858R+S768I (1, 3.6%), ALK (2, 7.1%), ROS1 (1, 3.6%), negative (5, 17.9%), and unknown (2, 7.1%)." (PMID 38269023, 2023). "Therefore, it will be important to study the specific effects of CD27 co-stimulation on Tregs in the context of restricted co-stimulation to a tumor antigen such as EGFR in relevant murine models and in combination with Treg depleting strategies, including sorafenib treatment." (PMID 37545491, 2023). "For the meta-regression analysis, we also selected the same 9 variables (year, region, phase, immunotherapy inhibitor, anti-angiogenic drug, tumor histology, study design, EGFR mutation, whether or not to combine chemotherapy)." (PMID 37614237, 2023). "This may be because cell signaling crosstalk between the tumor and the tumor environment impacts its mechanism of action, such as the prominent crosstalk of de-regulated EGFR and Ras activity with integrin, focal adhesion kinase (FAK), Src, Rac/Rho GTPases signaling." (PMID 37129645, 2023). "However, contrary to the findings of previous studies, we found that patients harboring compound EGFR mutations without 19del/L858R had a superior tumor response and a lengthier PFS timing than those with 19del/L858R." (PMID 37116899, 2023). "Therefore, the interaction of ANXA6 with the EGFR may be a potential mechanism for tumor drug resistance." (PMID 37129645, 2023). "Finally, Hashemkhani and co-workers investigated the use of cetuximab-conjugated Ag2S QDs for the delivery of 5-FU and 5-aminolevulinic acid (ALA) to achieve tumor-specific image-guided photodynamic therapy/chemotherapy combination in EGFR-overexpressing CRC cell lines." (PMID 37242756, 2023). "Therefore, we studied whether there is an association between EGFR, RANKL, RANK and OPG gene expression in the tumor and presence of bone metastases in patients with NSCLC." (PMID 37213294, 2023). "In addition to acting on macrophages, Exo-EGFR inhibits the tumor immune function of DCs." (PMID 37122754, 2023).
tumor (continued). "In the present study, the ratio of T790M/major EGFR mutation at pretreatment could not predict the outcome or tumor shrinkage after osimertinib administration." (PMID 38012343, 2023). "Also, EGF secretion by TAMs may activate EGFR on tumor cells, further upregulate VEGF/VEGFR signaling, and thus increase cancer cell proliferation and invasion." (PMID 38033495, 2023). "35d alone or with TKIs suppressed tumor growth in TKI-resistant LUAD tumors, including those with variant resistant mechanisms such as a common factor, nuclear PKCδ (found in >40% of the resistant LUADs), and EGFR C797S mutation (found in ∼15% of the resistant LUADs)." (PMID 37178919, 2023). "Our data suggest that in precancerous states and to prevent tumour relapse, EGFR activation—such as through EGF treatment—might provide a competitive advantage to wild-type cells in the presence of neighbours expressing the constitutively active form of a Ras oncogene." (PMID 37344586, 2023). "Furthermore, exosomal miR-210-3p may play a role in osimertinib resistance by inducing the EMT process in the tumor microenvironment of EGFR-mutant non-small cell lung cancer (NSCLC)." (PMID 36839784, 2023). "NF1 and EGFR co-altered samples thus may be phenotypically significant in tumor recurrence but rarely detected from the analysis of single biopsies or those originating from the resected portion of the CE tumor." (PMID 37770427, 2023). "Our findings, identifying a miR-145-5p/c-MYC/EGFR/MUC1/OCT4 network, provided further evidence demonstrating that the altered activity of non-coding RNAs either as loss of tumor suppressor activity or gain of oncogenic functions might play in the chemoresistance of metastatic lesions." (PMID 37598177, 2023). "In agreement with clinical experiences, our results also underline that the inhibition of EGFR might be able to reduce the proliferation rate of tumor cells to a limited extent, but this effect is not sufficient to eliminate them completely." (PMID 36834866, 2023). "EGFR gene amplification/overexpression is a genetic hallmark in adult GBM (observed ~40% of tumors), whereas this feature is only observed in 25% of pediatric cases; nevertheless, it is associated in a similar manner with higher proliferation and increased tumor grade." (PMID 36839989, 2023). "However, utilizing the protein expression of VEGF within tumor tissues as a significant biomarker for outcome after first‐ or second‐generation EGFR‐TKI may be difficult." (PMID 37605832, 2023). "Additionally, one may hypothesize that the reverse condition also stands and that ICI prior to cetuximab could modulate the tumor microenvironment and EGFR pathway, leading to improved responses to anti-EGFR therapy." (PMID 37370790, 2023). "Among the nine patients with BPM, driver mutations of primary tumours were determined by NGS, including EGFR mutations (5, 55.6%), which include 19del (4, 44.4%), L858R+A871E + MET (1, 11.1%), ALK (1, 11.1%), ROS1 (1, 11.1%), KRAS (1, 11.1%), and unknown (1, 11.1%)." (PMID 38269023, 2023). "EGFR targeting may be considered in a subgroup of EGFR positive tumours." (PMID 36399188, 2023). "The mechanisms underlying the poor response may include the lower PD-L1 expression, lower tumor mutational burden (TMB), and the immunosuppressive tumor microenvironment (TME) resulting from constitutive activation of the EGFR signaling pathway in EGFR-mutated NSCLC." (PMID 37766136, 2023). "However, tumor differentiation, as well as the presence of mutations (EGFR, KRAS, etc.)for adenocarcinoma were not significant predictors for DFS." (PMID 37370781, 2023). "In addition, YTHDF2 may act as a tumor suppressor to repress cell proliferation and growth by destabilizing EGFR mRNA in HCC cells." (PMID 36936652, 2023).
tumor (continued). "For instance, the activation of EGFR (epithelial growth factor) promotes tumor growth and TAM expansion, which further boost HGOS progression, leading to the hypothesis that EGFR signaling in HGOS cells releases secreted factors that favor the expansion of tumor-permissive M2 TAMs." (PMID 36614241, 2023). "In addition, we found that the expression of MUC17 decreased gradually with the increase of tumor malignancy, but was not correlated with EGFR mutation status." (PMID 36778111, 2023). "Thus, advanced understanding of endosomal EGFR signaling and how it may impact tumor viability are necessary before this strategy is viable for combination therapy with TKIs." (PMID 37752992, 2023). "Building on our earlier findings, which suggest that CD39 + CD8 + T cells may be enriched for cells recognising antigens within the tumour, we investigated whether EGFR-TKI acquired resistance could influence the TCR-Vβ diversity in pleural CD39 + CD8 + T cells." (PMID 38087217, 2023). "It was shown that EGFR may activate ATM, which is one of the main regulators and effectors of the DNA-damage-activated checkpoint system, which causes radiation resistance in EGFRvIII tumor cells." (PMID 37762559, 2023). "Interestingly, it was discovered that knockdown of METTL1 did not alter mRNA levels of cancer-related genes, but its translation efficiency was impaired, leading to a drop in cell cycle-related proteins such as CCNA2, CCND2, CDK6, CDK8 and EGFR, which affected tumor progression." (PMID 37710294, 2023). "PIK3CA amplification or mutations promote tumour infiltration and activate the PI3K/AKT/mTOR pathway, which suggests that PI3K/AKT/mTOR pathway activation might be related to resistance to 3rd-generation EGFR-TKIs." (PMID 37897649, 2023). "The study demonstrates a role for hepsin as a regulator of cell proliferation and tumor growth through TGFβ and EGFR pathways, warranting consideration of hepsin as a potential indirect upstream target for therapeutic inhibition of TGFβ and EGFR pathways in cancer." (PMID 37872868, 2023). "Importantly, the U118 tumor target cells display robust levels of WT EGFR, and coculture with the U118‐EGFRvIII cells resulted in a highly specific activation of the GCT02 CAR T cells, therefore, this cell line made excellent positive and negative controlled targets for the specificity screen." (PMID 36890859, 2023). "EGFR mutation status was not significant for predicting overall survival or tumor control." (PMID 36676186, 2023). "It has been determined that the PD-L1 expression varies during tumor progression due to communication between the tumor and the cells of immune system—the action of antitumor therapy, for example—against a background of the use of tyrosine kinase inhibitors that suppress the activity of EGFR or ALK." (PMID 36979782, 2023). "To evaluate whether ARTi can recapitulate drug activities in vivo, we xenotransplanted EGFRdel19::V5::dsRed::ARTi engineered PC-9 cells harboring the dox-inducible ARTi-shRNAmir and treated recipient mice upon tumor formation with either dox or the clinically approved EGFR inhibitor osimertinib." (PMID 37552050, 2023). "The resulting antibodies simultaneously target epidermal growth factor receptor (EGFR), programmed death-ligand 1 (PD-L1) and CD16a with two Fab fragments, resulting in specific cellular binding properties on EGFR/PD-L1 double positive tumor cells and a potent ADCC effect." (PMID 37081888, 2023). "Therefore, the combination of anti-VEGF monoclonal antibody and EGFR-TKI may be a valid anti-tumor strategy." (PMID 36910653, 2023).